PPT1 (palmitoyl-protein thioesterase 1)
Description:
Has thioesterase activity against fatty acid thioesters with 14 -18 carbons, including palmitoyl-CoA, S-palmitoyl-N-acetylcysteamine, and palmitoylated proteins. In contrast to PPT2, PPT1 can hydrolyze palmitoylated proteins and palmitoylcysteine.
Synonyms: CLN1; PPT; INCL
Tractability: Small molecule: it has a binding pocket of medium quality. Antibody: UniProt places it where antibodies can reach, with high confidence; its Gene Ontology location is reachable by antibodies, with high confidence; UniProt predicts a signal peptide or a membrane-spanning region. PROTAC: ubiquitination databases record sites on it; its protein half-life has been measured; a small molecule that binds it is known.
Target class: Enzyme; Hydrolase
Gene: Protein-coding gene on chromosome 1 (40,072,710 to 40,097,267, reverse strand). Ensembl gene ENSG00000131238.
Subcellular location: Lysosome; Secreted; Golgi apparatus; Endoplasmic reticulum
Subcellular location (Human Protein Atlas): Golgi apparatus; Vesicles
Pathways (Reactome):
Metabolism: Fatty acyl-CoA biosynthesis
Gene Ontology:
Molecular function: lysophosphatidic acid binding; palmitoyl-(protein) hydrolase activity; protein binding; sulfatide binding; long-chain fatty acyl-CoA hydrolase activity; palmitoyl hydrolase activity
Biological process: brain development; lipid catabolic process; lysosomal lumen acidification; membrane raft organization; negative regulation of apoptotic process; negative regulation of cell growth; negative regulation of neuron apoptotic process; negative regulation of toll-like receptor 9 signaling pathway; nervous system development; pinocytosis; positive regulation of pinocytosis; positive regulation of receptor-mediated endocytosis; protein depalmitoylation; protein transport; receptor-mediated endocytosis; endocytosis; fatty-acyl-CoA biosynthetic process; neuron development; protein catabolic process; regulation of synapse structure or activity; sphingolipid catabolic process
Cellular component: axon; endoplasmic reticulum; extracellular exosome; extracellular region; Golgi apparatus; lysosomal membrane; lysosome; membrane; membrane raft; nucleus; synaptic vesicle; cytosol; lysosomal lumen
Genetic constraint (gnomAD): Loss-of-function variants: 24 observed, 46.04 expected, observed/expected ratio (o/e) 0.52, 90% interval 0.38 to 0.73. The upper end of that interval is the gene's LOEUF score, 0.73, which puts it in group 3 of 6, group 1 being the genes least tolerant of losing a copy. Missense variants: 341 observed, 401.55 expected, observed/expected ratio (o/e) 0.85, 90% interval 0.78 to 0.93. Synonymous variants: 148 observed, 149.55 expected, observed/expected ratio (o/e) 0.99, 90% interval 0.87 to 1.13.
Gene-disease validity (ClinGen):
ClinGen rates the evidence that PPT1 causes each of these diseases.
neuronal ceroid lipofuscinosis (autosomal recessive): Definitive.
Homologues: Orthologues: chimpanzee PPT1 (99% identical), macaque PPT1 (97% identical), pig PPT1 (90% identical), dog PPT1 (90% identical), rabbit PPT1 (89% identical), guinea pig PPT1 (86% identical), rat Ppt1 (86% identical), mouse Ppt1 (85% identical), tropical clawed frog ppt1 (69% identical), zebrafish ppt1 (66% identical), Drosophila melanogaster Ppt1 (52% identical), Caenorhabditis elegans ppt-1 (48% identical). Paralogues in human: PPT2 (25% identical), DOLPP1 (15% identical).
Diseases named in the same sentence as PPT1 in open-access papers:
PPT1 is named in the same sentence as 123 diseases in open-access papers, as found by Europe PMC text mining. Sharing a sentence is not in itself a finding about the gene and the disease. The quoted sentences say what the papers report.
neuronal ceroid lipofuscinosis (68 papers, 2007 to 2026). "CLN1 disease, one of the most severe forms of neuronal ceroid lipofuscinosis (NCLs or Batten disease), is a rapidly progressing pediatric neurodegenerative disorder caused by mutations in the PPT1 gene." (PMID 41466111, 2025). "Deficiency of TPP1 and PPT1 have been linked to the neurodegenerative lysosomal storage disease neuronal ceroid lipofuscinosis (NCL), and ARL8B also has been linked to a lysosomal storage disorder, Niemann-Pick disease type C." (PMID 39070643, 2024). "Mutations in the depalmitoylase gene PPT1 cause infantile NCL (neuronal ceroid lipofuscinosis), an early-onset neurodegenerative disease." (PMID 38293675, 2023). "Loss-of-function mutations in the depalmitoylating enzyme palmitoyl protein thioesterase 1 (PPT1) cause neuronal ceroid lipofuscinosis (NCL), a devastating neurodegenerative disease." (PMID 35358180, 2022). "Last, loss-of-function mutations in the rLL protein palmitoyl thioesterase-1 (PPT-1) result in neuronal ceroid lipofuscinosis, a neurodegenerative lysosomal storage disorder." (PMID 35594347, 2022). "Mutations in the gene coding for PPT1 cause a lysosomal storage neurodegenerative disease known as infantile neuronal ceroid lipofuscinosis." (PMID 34659801, 2021). "We demonstrate that GFAP palmitoylation is regulated by PPT1, a palmitoylprotein thioesterase linked to a childhood neurodegenerative disorder, infantile neuronal ceroid lipofuscinosis." (PMID 33753498, 2021). "Mutations in the CLN1 gene encoding the palmitoyl-protein thioesterase-1 (PPT1) are the basis of infantile neuronal ceroid lipofuscinosis (INCL or CLN1)." (PMID 34451881, 2021). "PPT1 loss of function variants, in the homozygous or compound heterozygous state, were demonstrated to cause neuronal ceroid lipofuscinosis, an inherited, progressive neurodegenerative disease." (PMID 34948429, 2021). "Recently, a genetic association was reported between a variant in PPT1, a well-known candidate gene for neuronal ceroid lipofuscinosis (NCL), and PRA in MS." (PMID 32150541, 2020). "Mutation of the depalmitoylating enzyme palmitoyl-protein thioesterase 1 (PPT1) causes infantile neuronal ceroid lipofuscinosis (CLN1), a pediatric neurodegenerative disease." (PMID 30946007, 2019). "Specifically, mutations that disrupt PPT1 function cause the devastating neurodegenerative disease, infantile neuronal ceroid lipofuscinosis, emphasizing the importance of depalmitoylation in neuronal health." (PMID 31555119, 2019). "Palmitoyl-protein thioesterase 1 (PPT1) is a depalmitoylation enzyme that is mutated in cases of neuronal ceroid lipofuscinosis (NCL)." (PMID 30918483, 2019). "Mutations in the Ppt1 genes cause infantile neuronal ceroid lipofuscinosis, a severe neurodegenerative disease characterized by an accumulation of ceroid aggregates in lysosomes and leading to neuronal death." (PMID 29208753, 2018). "PPT1 is also a lysosomal enzyme and the dysregulation of this enzyme causes a lysosomal storage and neurodegenerative disorder; infantile neuronal ceroid lipofuscinosis." (PMID 30018533, 2018). "PPT1 has been heavily studied because it has been identified as the causative gene of the disease infantile neuronal ceroid lipofuscinosis." (PMID 28320309, 2017). "Mutations in the depalmitoylating enzyme gene, PPT1, cause the infantile form of Neuronal Ceroid Lipofuscinosis (NCL), an early onset neurodegenerative disease." (PMID 26731412, 2016). "In humans, loss of function mutations in PPT1 cause infantile neuronal ceroid lipofuscinosis, a severe pediatric neurodegenerative disease resulting in death by 10 years of age." (PMID 24705017, 2014). "Mutations in the human PPT1 gene are known to cause the neurodegenerative disease infantile neuronal ceroid lipofuscinosis (INCL)." (PMID 25277130, 2014).
neuronal ceroid lipofuscinosis (continued). "The mouse model of infantile neuronal ceroid lipofuscinosis, a neurodegenerative disease caused by palmitoyl-protein thioesterase-1 (PPT1) deficiency, manifests enhanced endoplasmic reticulum- and oxidative stress that lead to apoptotic cell demise." (PMID 24058332, 2013). "Ppt1 mutation can cause neuronal ceroid lipofuscinosis (NCL), a neurodegenerative disease." (PMID 37020861, 2023). "Similarly, studies have shown that PPT1 deficiency is one of the causes of neuronal ceroid lipofuscinosis (NCL), suggesting a unique function for PPT1 in brain development." (PMID 36286021, 2022). "Remarkably, the disruption of such cycling can cause severe physiological consequences; for example, a common natural mutation in ppt1 (c.451C > T) results in the dysfunction of PPT1 and thus an early form of neurodegenerative disease infantile neuronal ceroid lipofuscinosis (INCL)." (PMID 33753498, 2021). "PPT-1 deficient fibroblasts from patients suffering from infantile neuronal ceroid lipofuscinosis (INCL) or murine cells harboring a disrupted Ppt1/Cln1 gene revealed reduced caspase activation, Bid-cleavage, and cytochrome C release by mitochondrial outer membrane permeabilization (MOMP)." (PMID 34063813, 2021). "PPT1 is a small glycoprotein associated with infantile neuronal ceroid lipofuscinosis (INCL)." (PMID 27869176, 2016). "The infantile form of neuronal ceroid lipofuscinosis (also known as infantile Batten disease) is caused by hereditary deficiency of a lysosomal enzyme, palmitoyl-protein thioesterase-1 (PPT1), and is characterized by severe cortical degeneration with blindness and cognitive and motor dysfunction." (PMID 18021406, 2007). "Infantile neuronal ceroid lipofuscinosis (INCL) is the fastest developing and most severe type of NCL caused by mutations in the CLN1 gene, which encodes palmityl protein thioesterase-1 (PPT1)." (PMID 35628400, 2022). "Infantile neuronal ceroid lipofuscinosis (INCL), the most severe form of neuronal ceroid lipofuscinoses, is caused by mutations in the lysosomal enzyme palmitoyl protein thioesterase 1 (PPT1)." (PMID 35628400, 2022). "Similarly, we found a stop-gain variant in PPT1 (p.R48X) in an early onset (61 years) familial AD patient; PPT1 loss of function mutations have been previously demonstrated to cause an adult form of neuronal ceroid lipofuscinosis (NCL)." (PMID 34948429, 2021). "Infantile neuronal ceroid lipofuscinosis (INCL) is a fatal neurodegenerative disorder caused by a deficiency of palmitoyl-protein thioesterase-1 (PPT1)." (PMID 23139814, 2012). "The neuronal ceroid lipofuscinosis family of lysosomal storage diseases, also called CLN1 disease, is characterized by the deficiency of palmitoyl-protein thioesterase 1 (PPT1)." (PMID 41629288, 2026). "For instance, a six-month PPT1 mimetic treatment significantly reduced microglial activation in Ppt1−/− mice, a model of Infantile Neuronal Ceroid Lipofuscinosis." (PMID 40703511, 2025). "The depalmitoylating enzyme, palmitoyl-protein thioesterase 1 (PPT1), is associated with the devastating pediatric neurodegenerative condition, infantile neuronal ceroid lipofuscinosis (CLN1)." (PMID 38798824, 2024). "Accordingly, mutations in the gene encoding PPT1, CLN1, cause infantile neuronal ceroid lipofuscinosis (CLN1), a fatal pediatric neurodegenerative disease that presents with sensory loss, motor regression, and seizure." (PMID 38798824, 2024). "CLN1 gene encodes for the lysosomal enzyme palmitoyl-protein thioesterase 1 (PPT1) and mutations in this gene cause the Infantile NCL (INCL), the most severe form of NCL." (PMID 33800050, 2021).
neuronal ceroid lipofuscinosis (continued). "The dysfunction of PPT1 (PPT1-KI, infantile neuronal ceroid lipofuscinosis [INCL] mouse model), which catalyze the depalmitoylation process, results in serious neurodegeneration accompanied by severe astrogliosis in the brain." (PMID 33753498, 2021). "NCL type 1 (CLN1) disease, also termed infantile neuronal ceroid lipofuscinosis (INCL) or infantile Batten disease, is caused by mutations in the PPT1 gene on chromosome 1p34.213." (PMID 31578378, 2019). "Infantile neuronal ceroid lipofuscinosis (INCL, Infantile Batten disease) is a neurodegenerative lysosomal storage disease caused by a deficiency in palmitoyl protein thioesterase-1 (PPT1)." (PMID 26238334, 2015). "The PPT1 knockout mouse is an excellent model for infantile neuronal ceroid lipofuscinosis, recapitulating the major findings in the disease." (PMID 18021406, 2007). "The most severe form of NCL, infantile neuronal ceroid lipofuscinosis (INCL), is caused by mutations in the CLN1 gene, resulting in a deficiency of the lysosomal enzyme, palmitoyl protein thioesterase 1 (PPT1)." (PMID 17565660, 2007). "One class of diseases called infantile neuronal ceroid lipofuscinosis (CLN1 disease) is caused by a mutation in CLN1, which encodes palmitoyl-protein thioesterase 1 (PPT1) and may have several phenotypes and types of symptom progressions." (PMID 36766729, 2023). "CLN1 disease, also called infantile neuronal ceroid lipofuscinosis (NCL) or infantile Batten disease, is a fatal neurodegenerative lysosomal storage disorder resulting from mutations in the CLN1 gene encoding the soluble lysosomal enzyme palmitoyl-protein thioesterase 1 (PPT1)." (PMID 36040802, 2022). "Lack of PPT1 usually leads to a genetic disease named infantile neuronal ceroid lipofuscinosis, which is caused by substantial death of cortical neurons." (PMID 35004674, 2021). "Mutations in GUSB, CLN6, and PPT1 cause Sly disease, neuronal ceroid lipofuscinosis (CLN6), and neuronal ceroid lipofuscinosis (CLN1), respectively, whereas mutations in GALNS and NAGA cause Morquio A disease and Schindler disease/Kanzaki disease, respectively." (PMID 34867278, 2021). "Finally, mutations in genes encoding the depalmitoylating enzyme PPT1 and the palmitoylated cysteine string protein (CSP; DNAJC5) cause neuronal ceroid lipofuscinosis a lysosomal-storage neurodegenerative disease." (PMID 34659801, 2021). "Mutations in the Infantile NCL (CLN1) gene, which encodes PPT1, cause the infantile form of NCL." (PMID 31555119, 2019). "Infantile neuronal ceroid lipofuscinosis (INCL), a childhood neurodegenerative disease, results from mutations in the CLN1 gene encoding the lysosomal enzyme, palmitoyl‐protein thioesterase 1 (PPT1) [Biochim Biophys Acta 1832 (2013) 1806, Hum Mutat (2012) 63, Biochim Biophys Acta 1832 (2013) 1881]." (PMID 26648046, 2016). "PPT1 protein is a small glycoprotein involved in the catabolism of lipid-modified proteins during lysosomal degradation, and mutations in the PPT1 gene cause infantile neuronal ceroid lipofuscinosis 1 (CLN1; OMIM #256730) and neuronal ceroid lipofuscinosis 4 (CLN4; OMIM #204300)." (PMID 24244371, 2013). "Neuronal ceroid lipofuscinosis type 1 (CLN1), also known as infantile neuronal ceroid lipofuscinosis (INCL), is a rare (1 in 100,000 births), but one of the most lethal, inherited neurodegenerative lysosomal storage disorders caused by mutations in the PPT1 gene resulting in PPT1 deficiency." (PMID 37324388, 2023). "PPT1 is encoded by CLN1, and mutations in this gene are associated with a severe neurodegenerative disorder known as infantile neuronal ceroid lipofuscinosis (INCL, also known as Batten disease)." (PMID 38964324, 2024). "In addition to this most prevalent CLN1 disease ‘classic infantile NCL’ (INCL) variant, patients harboring mutations in the PPT1 gene might develop first clinical symptoms later in life, and present with a more slowly progressing late-infantile, juvenile or adult onset NCL22–28." (PMID 31578378, 2019).
neuronal ceroid lipofuscinosis (continued). "Moreover, S100B production and subsequent RAGE expression can lead to neuronal apoptosis mediated by ER-stress in infantile neuronal ceroid lipofuscinosis (INCL) and palmitoyl-protein thioesterase-1- (PPT1-) KO mice." (PMID 27313835, 2016). "Some years later, a similar approach was tested in an animal model and three patients with neuronal ceroid lipofuscinosis (NCL) (lacking the functional palmitoyl protein thioesterase 1—PPT1) by transplanting them with genetically engineered bone marrow-derived HSCs overexpressing PPT1." (PMID 34685661, 2021). "In murine primary neurons and brain tissue, PPT1 is localized in synaptosomes and synaptic vesicles but not in lysosomes, and, as such, abnormal synaptic functioning could play a role in the CLN1 form of neuronal ceroid lipofuscinosis." (PMID 30541930, 2019).
lysosomal storage disorder (17 papers, 2007 to 2026). "CLN1 disease, caused by mutations in the PPT1 gene, is a fatal neurodegenerative lysosomal storage disorder." (PMID 41977268, 2026). "Instead of proteins with chaperone or redox function, PPT1 KO lipofuscin exhibited accretion of several proteins implicated in NCLs and other lysosomal storage disorders (SAP, CATD, TPP1, SCRB2, ASAH1)." (PMID 40166029, 2025). "This lysosomal storage disorder results from a deficiency in the Palmitoyl Protein Thioesterase 1 (PPT1) enzyme—a lysosomal hydrolase which cleaves fatty acid chains such as palmitate from lipid-modified proteins." (PMID 33561134, 2021). "PPT1 has been shown to regulate lysosomal acidification via the lysosomal targeting of the V0a1 vacuolar ATPase (vATPase), and altered lysosomal pH underlies many lysosomal storage disorders." (PMID 38964324, 2024). "Palmitoyl-protein thioesterase 1 (PPT1), an endo-lysosomal protein, is the first known depalmitoylating enzyme to be linked to a fatal genetic lysosomal storage disorder in neurons, neuronal ceroid lipofuscinoses (NCLs)." (PMID 33653086, 2021). "Markers of an intense inflammatory response, noted at 5 and 8 months, may be somewhat unique to PPT1 deficiency and other lysosomal storage diseases and were not shared by several other available neurodegenerative disease models." (PMID 18021406, 2007).